CAMKK2 (calcium/calmodulin dependent protein kinase kinase 2)
Description:
Calcium/calmodulin-dependent protein kinase belonging to a proposed calcium-triggered signaling cascade involved in a number of cellular processes. Isoform 1, isoform 2 and isoform 3 phosphorylate CAMK1 and CAMK4. Isoform 3 phosphorylates CAMK1D. Isoform 4, isoform 5 and isoform 6 lacking part of the calmodulin-binding domain are inactive. Efficiently phosphorylates 5'-AMP-activated protein kinase (AMPK) trimer, including that consisting of PRKAA1, PRKAB1 and PRKAG1. This phosphorylation is stimulated in response to Ca(2+) signals (By similarity). Seems to be involved in hippocampal activation of CREB1 (By similarity). May play a role in neurite growth. Isoform 3 may promote neurite elongation, while isoform 1 may promoter neurite branching.
Synonyms: CAMKKB; KIAA0787; CAMKK; MGC15254
Tractability: Small molecule: a structure with a bound ligand is known; a high-quality ligand is known; it belongs to a druggable protein family. PROTAC: ubiquitination databases record sites on it; its protein half-life has been measured; a small molecule that binds it is known.
Target class: Enzyme; Protein Kinase; Kinase; Other protein kinase group; Other protein kinase CAMKK family; Other protein kinase Meta subfamily
Chemical probes: SGC-CAMKK2-1 (high quality), STO609
Safety:
Unwanted effects reported when the protein is acted on. In parentheses: how it was acted on, where the effect was seen, and who reports it.
cardiac arrhythmia (cardiovascular system; source: Lamore et al. (2017))
Gene: Protein-coding gene on chromosome 12 (121,237,675 to 121,298,308, reverse strand). Ensembl gene ENSG00000110931.
Subcellular location: Nucleus; Cytoplasm; Cell projection, neuron projection
Subcellular location (Human Protein Atlas): Cytosol
Pathways (Reactome):
Neuronal System: Activation of AMPK downstream of NMDARs; Activation of RAC1 downstream of NMDARs; CREB1 phosphorylation through the activation of CaMKII/CaMKK/CaMKIV cascasde
Signal Transduction: CaMK IV-mediated phosphorylation of CREB
Gene Ontology:
Molecular function: calcium ion binding; calmodulin binding; protein tyrosine kinase activity; ATP binding; calcium/calmodulin-dependent protein kinase activity; protein kinase activity; protein serine kinase activity
Biological process: CAMKK-AMPK signaling cascade; positive regulation of autophagy of mitochondrion; protein autophosphorylation; protein phosphorylation; calcium-mediated signaling; cellular response to reactive oxygen species; MAPK cascade; positive regulation of DNA-templated transcription; regulation of protein kinase activity
Cellular component: cytoplasm; cytosol; nucleus; nucleoplasm; neuron projection
Genetic constraint (gnomAD): Loss-of-function variants: 28 observed, 59.13 expected, observed/expected ratio (o/e) 0.47, 90% interval 0.35 to 0.65. The upper end of that interval is the gene's LOEUF score, 0.65, which puts it in group 2 of 6, group 1 being the genes least tolerant of losing a copy. Missense variants: 614 observed, 756.27 expected, observed/expected ratio (o/e) 0.81, 90% interval 0.76 to 0.87. Synonymous variants: 309 observed, 305.27 expected, observed/expected ratio (o/e) 1.01, 90% interval 0.92 to 1.11.
Homologues: Orthologues: chimpanzee CAMKK2 (100% identical), macaque CAMKK2 (92% identical), mouse Camkk2 (92% identical), dog CAMKK2 (91% identical), pig CAMKK2 (91% identical), rabbit CAMKK2 (88% identical), rat Camkk2 (86% identical), guinea pig CAMKK2 (86% identical). Paralogues in human: CAMKK1 (52% identical), DCLK2 (24% identical), DCLK1 (23% identical), STK11 (20% identical), CAMK2D (19% identical), DCLK3 (19% identical), CAMK2G (19% identical), CAMK2B (19% identical), CAMK2A (19% identical), CAMK1D (17% identical), CAMK1 (17% identical), CAMK1G (17% identical), and 10 more.
Diseases named in the same sentence as CAMKK2 in open-access papers:
CAMKK2 is named in the same sentence as 132 diseases in open-access papers, as found by Europe PMC text mining. Sharing a sentence is not in itself a finding about the gene and the disease. The quoted sentences say what the papers report.
prostate carcinoma (39 papers, 2013 to 2025). A carcinoma that arises from epithelial cells of the prostate gland. "For example, research using patient tumour samples and a xenograft mouse model of castration-resistant prostate cancer found that disease progression was linked to increased CaMKK2-AMPK signaling." (PMID 39268917, 2024). "Increased expression of CaMKK2 correlates with greater prostate cancer aggressiveness and poorer prognosis, and is associated with reduced patient survival." (PMID 39268917, 2024). "Subsequently in vivo studies have shown that knocking out CAMKK2 in a transgenic model of prostate cancer driven by phosphatase and tensin homologue (PTEN) loss impairs tumorigenesis." (PMID 34725334, 2021). "A recent report showed that knocking out CAMKK2 in a transgenic mouse model of prostate cancer driven by PTEN loss impairs tumorigenesis." (PMID 34725334, 2021). "The upregulation of CAMKK2 is associated with hepatic cancer and prostate cancer, while the downregulation of CAMKK2 is associated with human schizophrenia and bipolar disorders." (PMID 33082841, 2020). "CaMKK2 is a known tumor promotor whose expression is linked to the upregulation of the androgen receptor, a key step in castrate-resistant prostate cancer." (PMID 29914450, 2018). "Specifically, we propose that CAMKK2 enables metabolic syndrome, which causes increased levels of circulating insulin or some insulin-like molecule that can promote oncogenic mTOR signaling in distant prostate cancer cells." (PMID 35741020, 2022). "Furthermore, Gemin4 is known to be regulated by the AR and associates with prostate cancer progression, which is highly relevant in the context of prostate cancer and CaMKK2 biology as the AR is also a major driver of CaMKK2 expression, disease progression and biology." (PMID 34725334, 2021). "Among all the molecules involved in the Calcium signaling pathway, the pro-tumorigenic role of CAMKK2 in prostate cancer was widely established." (PMID 40746562, 2025). "CaMKK2 is a major target gene of the androgen receptor and plays a key role in driving prostate cancer progression." (PMID 39268917, 2024). "Given the compelling data implicating CaMKK2 as a major driver of prostate cancer, it is now considered a highly attractive therapeutic target." (PMID 39268917, 2024). "Taken together, these findings demonstrate that CaMKK2 plays a key role in promoting lipogenesis in prostate cancer independently of AMPK." (PMID 39268917, 2024). "Knockdown of CaMKK2 in the prostate cancer cell line LNCaP results in a significant reduction in δ-COP protein levels, along with a reduction in α-COP." (PMID 36815702, 2023). "CAMKK2 is generally upregulated in several cancers, including prostate cancer, and high expression of CAMKK2 was correlated with poor overall survival in hepatocellular carcinoma and glioma 48-50." (PMID 36606188, 2022). "Because of this direct regulation by AR, CAMKK2’s functions in prostate cancer were largely assumed to be limited to classic, AR+ adenocarcinomas." (PMID 35741020, 2022). "Both syngeneic tumors grew more slowly in the KO mice indicating that cancer cell-extrinsic CAMKK2 promotes prostate cancer progression." (PMID 35741020, 2022). "One direct AR downstream target that promotes prostate cancer progression is the calcium-calmodulin-dependent protein kinase kinase 2 (CAMKK2)." (PMID 35741020, 2022). "To date, CAMKK2’s oncogenic effects in prostate cancer have solely been attributed to its known cancer cell-autonomous functions." (PMID 35741020, 2022). "Cohorts of mice were sacrificed at 15 and 30 weeks to study the role of CAMKK2 in prostate cancer initiation and progression, respectively." (PMID 35741020, 2022). "CaMKK2 levels have been found to be elevated in clinical samples of prostate cancer, where it regulates cancer cell growth." (PMID 35214061, 2022).
prostate carcinoma (continued). "Systemic Camkk2 ablation slowed disease progression in the TRAMP GEMM of prostate cancer similar to what was observed in the Pb-Cre4;Ptenf/f GEMM of prostate cancer." (PMID 35741020, 2022). "Collectively, these metabolic data indicate that CAMKK2 inhibition impacts symptoms of metabolic syndrome including sustained improvements in insulin sensitivity in preclinical models of prostate cancer." (PMID 35741020, 2022). "Unlike what was observed in Pb-Cre4;Ptenf/f mice, at 30 weeks TRAMP;Camkk2−/− mice exhibited relapsed local prostate cancer progression." (PMID 35741020, 2022). "Although the data presented here provide compelling new evidence for CAMKK2 functions in prostate cancer progression and potentially related effects on systemic metabolism, we are cognizant that this initial study has several caveats." (PMID 35741020, 2022). "In this study, we explored the involvement of LKB1 and CaMKK2 in the mechanism whereby capsaicin induces AMPK activation in prostate cancer cells." (PMID 35214061, 2022). "Taken together, CAMKK2 inhibition suppressed the metastatic colonization of NEPC tumors in a HFD-driven GEMM of aggressive prostate cancer." (PMID 35741020, 2022). "CAMKK2’s oncogenic roles in prostate cancer cell biology have logically led to investigations into CAMKK2’s pro-cancer roles in vivo." (PMID 35741020, 2022). "Given the multiple effects of Camkk2 ablation on cancer and macrometabolism, perhaps not surprisingly, here we observed for the first time an additional cancer cell-extrinsic role for CAMKK2 in prostate cancer progression." (PMID 35741020, 2022). "Together, these data indicate that, in addition to cancer cell-intrinsic roles, CAMKK2 mediates prostate cancer progression via tumor-extrinsic mechanisms." (PMID 35741020, 2022). "To assess the impact of CaMKK2 on membrane trafficking and organelle structure, we generated a stable knockdown of CAMKK2 in a prostate cancer cell line, LNCaP, using two independent shRNA constructs." (PMID 34725334, 2021). "Because our cell lines are prostate cancer derived, we chose to explore the interaction between Gemin4 and CaMKK2 further." (PMID 34725334, 2021). "We and others have shown that CAMKK2 is an important regulator of prostate cancer growth and plays a pro-tumorigenic role in a number of other cancer types." (PMID 34725334, 2021). "Given the interest in developing CAMKK2 inhibitors for the treatment of diseases including prostate cancer, these findings also have implications for combination therapy and for future studies focussing on molecular cancer subtypes." (PMID 34725334, 2021). "In a Pten-deleted prostate cancer mouse model, Camkk2 deletion or CAMKKβ pharmacological inhibition has been shown to suppress prostate tumorigenesis and reduce de novo lipogenesis, whereas Prkab1 (AMPK-β1) and Pten co-deletion accelerates tumor progression." (PMID 32630372, 2020). "In support of this concept, siRNA-mediated silencing of CAMKK2 expression in prostate cancer cells has been shown to increase the percentage of cells in G1 phase." (PMID 31942031, 2020). "The presence of the AMPK kinase CAMKK2 has been shown in the nucleus of prostate cancer cells, and nuclear AMPKα1 was recently shown to be phosphorylated by CAMKK in HeLa and A549 lung cancer cells." (PMID 32903688, 2020). "There are seemingly conflicting reports on the role of CAMKK2 in LNCaP prostate cancer cell lines, indicating that further studies are required." (PMID 31941153, 2020). "Simultaneously, Zyflamend inhibits CaMKK2, a tumor promotor that is over-expressed in many cancers, including castrate-resistant prostate cancer." (PMID 29914450, 2018). "The dichotomy between decreased CaMKK2 activity and schizophrenia, and increased CaMKK2 activity and prostate cancer, is borne out by an inverse co-morbidity between the two diseases." (PMID 28230171, 2017).
prostate carcinoma (continued). "Notably, the same study showed that either pharmacological inhibition or genetic deletion of CaMKK2 provided protection against prostate cancer development." (PMID 39268917, 2024). "We recently undertook a study to learn more about the role of CaMKK2 in prostate cancer which commenced with a characterisation of CaMKK2 protein interactions and led us to investigate effects on Golgi trafficking and lysosome function in cancer cell proliferation." (PMID 36815702, 2023). "However, prior reports suggesting roles for CAMKK2 in an AR- cell line in culture and here in vivo indicate roles for CAMKK2 even in AR-indifferent prostate cancers." (PMID 35741020, 2022). "While CAMKK2 has also been described to signal through CAMKI, CAMKIV, and occasionally AKT, it is currently unknown if these alternative CAMKK2 substrates have roles in prostate cancer." (PMID 35741020, 2022). "Further, we propose that CAMKK2 inhibition may also help combat common metabolic comorbidities in men with advanced prostate cancer." (PMID 35741020, 2022). "Despite early studies linking calcium-calmodulin protein kinase kinase 2 (CAMKK2) to prostate cancer cell migration and invasion, the role of CAMKK2 in metastasis in vivo remains unclear." (PMID 35741020, 2022). "Given the differences in circulating insulin levels, a known regulator of cell growth, we hypothesized that systemic CAMKK2 could promote prostate cancer cell growth and disease progression in part through cancer cell-extrinsic mechanisms." (PMID 35741020, 2022). "In addition, genetic targeting of Camkk2 in immune-intact mouse models of obesity-driven prostate cancer demonstrated simultaneous anti-cancer efficacy and improvements in whole-body metabolic homeostasis that we propose may be linked via a novel tumor-extrinsic, CAMKK2-mediated mechanism of action." (PMID 35741020, 2022). "To separate CAMKK2’s tumor extrinsic functions from its intrinsic functions in cancer, we subcutaneously injected cells from two syngeneic, Camkk2-intact/WT mouse prostate cancer lines (RM-9 and TRAMP-C2) into litter-matched Camkk2+/+ (WT) or Camkk2−/− (KO) host mice." (PMID 35741020, 2022). "Based on prior reports studying CAMKK2 in the liver and pancreas, we speculate that CAMKK2 activity in one or both organs may play a significant role in prostate cancer progression." (PMID 35741020, 2022). "First, our data suggest that CAMKK2 inhibitors could have value in the treatment of distant metastases and/or NEPC, leading causes of prostate cancer mortality." (PMID 35741020, 2022). "Therefore, CaMKK2 results overexpressed in prostate cancer as well, in part due to androgen-receptor hyperactivity." (PMID 35409187, 2022). "Our data suggest that treatment of primary prostate cancer may necessitate that CAMKK2 inhibitors be combined with additional therapies to overcome the localized resistance mechanisms." (PMID 35741020, 2022). "AR activity sustains CAMKK2 expression and this supports prostate cancer cell proliferation." (PMID 34725334, 2021). "Furthermore, inhibition and knockdown of CAMKK2 impaired androgen-responsive cell growth of prostate cancer cells." (PMID 34725334, 2021). "CAMKK2 is upregulated in prostate cancer directly through the androgen receptor." (PMID 31941153, 2020). "The link between cancer and CAMKK2 is well documented in prostate cancer." (PMID 31941153, 2020). "For instance, calcium/calmodulin-dependent kinase kinase 2 (CAMKK2) has been identified as one of the targets of the AR in both androgen-sensitive and castrate-resistant prostate cancer cell lines since the AR was recruited to the promoter of CAMKK2 in both stages of disease." (PMID 32927797, 2020). "Prostate carcinoma cells have a preference to form bone metastasis driven by the androgen receptor, which induces the expression of CaMKK2 as its key downstream signaling protein playing a fundamental role in tumor cell migration and invasiveness via the CaMKK2/AMPK pathway." (PMID 31991573, 2020).
prostate carcinoma (continued). "Taken together, these findings are in accord with studies that have consistently identified that CAMKK2 was overexpressed in human prostate tumor biopsies, highlighting the significance of AR-CAMKK2-AMPK signaling in mediating energy metabolism in prostate cancer." (PMID 32927797, 2020). "In prostate cancer, CAMKK2 is amplified in up to 6.3% of patients, however it is currently unknown if CAMKK2 amplification promotes AMPK activity in the clinic." (PMID 32630372, 2020). "Because AR activation promotes the expression of CAMKK271, an AMPKα1 activator, it is possible that the synergistic effect of androgen on the killing of prostate cancer cells by YM155 also or alternatively occurs through enhanced activation of AMPKα by elevated levels of CAMKK2 induced by androgen." (PMID 31395901, 2019). "Elevated CaMKK2 activity has been shown to play an adverse role in HCC as well as prostate cancer." (PMID 28230171, 2017). "Some studies have reported CaMKK2 involvement in the pathophysiology of prostatic cancer, where CaMKK2 is identified as an androgen target gene and increased expression and activation of CaMKK2/AMPK signaling affects cell migration, invasion and anabolic pathways." (PMID 25153723, 2014). "However, CaMKK2 inhibition may offer a significant improvement over androgen deprivation therapy as it not only prevents prostate cancer progression but also protects against metabolic syndrome, improves insulin sensitivity, and increases bone mass." (PMID 39268917, 2024). "Moreover, if CAMKK2’s hepatic functions are proven to be a major driver of prostate cancer progression, this could present new opportunities from a drug development/pharmacokinetic standpoint, given that many drugs often accumulate in the liver." (PMID 35741020, 2022). "However, it is unknown whether CAMKK2 inhibition in prostate cancer models would also offset symptoms of metabolic syndrome, a common comorbidity for men with advancing prostate cancer." (PMID 35741020, 2022). "While CAMKK2 is an interesting therapeutic target due to its role in prostate cancer cell biology, prior reports indicate that CAMKK2 inhibitors may have additional benefits for prostate cancer patients." (PMID 35741020, 2022). "Therefore, it has been shown that CaMKK2 is a target gene of AR in prostate cancer." (PMID 35409187, 2022). "We also review the role of the CaMKK2-AMPK pathway in the regulation of whole-body energy metabolism and brain function, and comment on emerging evidence that suggests paradoxical roles for CaMKK2 and AMPK in fatty liver disease and prostate cancer." (PMID 39268917, 2024). "To understand what role CAMKK2 played in the progression of aggressive prostate cancer, we crossed TRAMP mice with Camkk2−/− mice to create TRAMP;Camkk2−/− (KO) and matched TRAMP;Camkk2+/+ (WT) mice." (PMID 35741020, 2022). "Previous work using a germline knockout (KO) of Camkk2 in the Pb-Cre;Ptenf/f genetic mouse model (GEMM) of prostate cancer demonstrated decreased incidence and severity of prostatic intraepithelial neoplasia (PIN) compared to Camkk2 WT mice." (PMID 35741020, 2022). "AR directly regulates CAMKK2 and is highly expressed in normal prostate with elevated expression in both AR-sensitive and CRPC models of prostate cancer." (PMID 23573093, 2013). "Paradoxical roles exist for CaMKK2 and AMPK in liver function and prostate cancer." (PMID 39268917, 2024). "Although the initial report of CAMKK2’s functional role in prostate cancer noted effects on prostate cancer cell migration and invasion, to our knowledge, CAMKK2’s role in prostate cancer metastasis in vivo had not been described until this study." (PMID 35741020, 2022). "Although the role of CaMKK2 in prostate cancer has been recently revealed, it does not appear to have an essential effect on growth regulation." (PMID 35214061, 2022).